SLC30A10 (solute carrier family 30 member 10)
Diseases named in the same sentence as SLC30A10 in open-access papers (continued):
Sharing a sentence is not in itself a finding about the gene and the disease.
SLC30A10 also shares sentences with these, for which no sentence is quoted: movement disorder (3 papers); acrodermatitis enteropathica (2); congenital disorder of glycosylation type IIn (2); neurologic disease (2); transient neonatal zinc deficiency (2); amyotrophic lateral sclerosis (1); anemia (1); Ataxia (1); attention deficit-hyperactivity disorder (1); basal cell carcinoma (1); calcium oxalate kidney stones (1); cardiovascular disease (1); cerebrovascular disease (1); cholangitis (1); colorectal tumor (1); depression (1); fatty liver (1); Friedreich ataxia (1); gastric cancer (1); generalized dystonia (1); Huntington disease (1); immune dysfunction (1); intrahepatic bile duct carcinoma (1); ischemia (1); liver dysfunction (1); lymph node metastasis (1); metabolic syndrome (1); neuroblastoma (1); neuroferritinopathy (1); obstruction of bile duct (1).
A further 5 diseases each share a sentence with SLC30A10 in 1 paper.